MGP (matrix Gla protein)
Diseases named in the same sentence as MGP in open-access papers (continued):
Sharing a sentence is not in itself a finding about the gene and the disease.
osteoporosis (13 papers, 2016 to 2025). A condition of reduced bone mass, with decreased cortical thickness and a decrease in the number and size of the trabeculae of cancellous bone (but normal chemical composition), resulting in increased fracture incidence. "A deficiency in Vitamin K can impair the function of OC and MGP, increasing the risk of osteoporosis and fractures." (PMID 38162659, 2023). "While VC patients with high risk are often accompanied with osteoporosis, Matrix Gla protein (MGP) and osteocalcin are important factors for their regulation." (PMID 34399835, 2021). "Further clarification of the role of vitamin K deficiency on the pathogenesis of various diseases such as osteoporosis, osteoarthrosis, or vascular calcification will be required in view of MGP metabolism." (PMID 32605143, 2020). "Furthermore, we demonstrated that using recombinant adeno-associated virus 9 (rAAV9) to silence MGP has the effect of alleviating bone loss and reversing the excessive bone marrow adipose tissue in mice with osteoporosis." (PMID 40216750, 2025). "Notably, in vivo knockdown of MGP using rAAV9 effectively ameliorates excessive marrow adipogenesis and bone loss associated with osteoporosis." (PMID 40216750, 2025). "To clarify the impact of MGP on osteoporosis, we investigated the function of MGP in MSC adipogenic differentiation." (PMID 40216750, 2025). "In this study, we detected elevated MGP expression in bone marrow MSCs from patients with osteoporosis and osteoporotic mouse models." (PMID 40216750, 2025). "To achieve this goal, we established an OVX-induced osteoporosis model and employed rAAV9 for in vivo MGP knockdown." (PMID 40216750, 2025). "After validating MGP and its regulatory mechanisms in adipogenic differentiation in vitro, we aimed to assess its potential as a therapeutic target for osteoporosis in vivo." (PMID 40216750, 2025). "By integrating cis-eQTL, pQTL, and RNA-seq data, four candidate genes were identified with significant causal effects on osteoporosis risk, including COL6A2, CPXM1, MGP, and SPARC." (PMID 41029778, 2025). "In this study, we explored the role of MGP in MSC adipogenesis in osteoporosis, both in vitro and in vivo." (PMID 40216750, 2025). "We found that the serum concentration of MGP in OP patients increased significantly, and was negatively correlated with the T-score of osteoporosis." (PMID 37187293, 2023). "Mechanistically, reduced APPL1 impaired the osteogenic differentiation of MSCs by facilitating MGP expression to disrupt the BMP2 pathway in osteoporosis." (PMID 37187293, 2023). "In animal experiments, knockout mice models of MGP, displayed both vascular calcification and osteoporosis." (PMID 27149062, 2016). "Besides, MGP expression level was significantly increased in tissues from the mice with postmenopausal osteoporosis and MSCs from OP patients, as shown by immunofluorescence staining." (PMID 40216750, 2025). "Importantly we demonstrated the therapeutic potential of sh-MGP in vivo, suggesting its potential in osteoporosis treatment." (PMID 40216750, 2025). "However, the mechanisms through which MGP regulates osteoporosis and bone-fat imbalance in MSCs are still unclear." (PMID 40216750, 2025). "Taken together, these results indicate that MGP is critically involved in osteoporosis." (PMID 40216750, 2025). "Moreover, we found a robust correlation between MGP expression and the severity of osteoporosis, revealing the critical involvement of MGP in osteoporotic progression." (PMID 40216750, 2025). "Additionally, IHC staining revealed that MGP expression was significantly upregulated in both the postmenopausal osteoporosis and senile osteoporosis groups compared to the control group." (PMID 40216750, 2025). "Moreover, we detected the concentration of MGP in the serum of patients with osteoporosis and healthy volunteers by ELISA." (PMID 37187293, 2023).
osteoporosis (continued). "In conclusion, we identified APPL1 may be an important regulator in osteoporosis, which inhibited the expression of MGP, activated the BMP2 pathway, and promoted the osteogenic differentiation of MSCs." (PMID 37187293, 2023). "These two findings indicated the possible role of MGP on the pathogenesis of osteoporosis." (PMID 32605143, 2020). "In our study, we verified that MGP governs adipogenic differentiation by upregulating the transcription of FABP3 in MSCs and contributes to osteoporosis by affecting the Ca2+/CaMKII/RIP140 pathway." (PMID 40216750, 2025). "Collectively, these findings not only uncover a novel regulatory mechanism of MGP in MSC adipogenesis, but also offer valuable insights for the treatment of osteoporosis." (PMID 40216750, 2025). "In this study, we confirmed that the expression of MGP upregulated in osteoporosis and has a negative correlation with BMD (bone mineral density)." (PMID 40216750, 2025). "In summary, our research has unveiled the regulatory role of MGP/Ca2+/CaMKII/RIP140/FABP3 axis in adipogenic differentiation in MSC and it might be a promising approach for osteoporosis treatment." (PMID 40216750, 2025).
coronary artery calcification (10 papers, 2013 to 2025). Calcification of the coronary artery, used as a measure of coronary atherosclerosis, a risk factor for myocardial infarction. "The strong inverse correlation between serum t-ucMGP levels and coronary artery calcification score, as well as the positive association with eGFR, indicates that serum MGP levels are an important biomarker of renal disease status in this cohort." (PMID 41465069, 2025). "MGP polymorphisms have been linked to coronary artery calcification in patients, while in mice genetic loss of MGP leads to cartilaginous metaplasia and extensive calcification of the tunica media." (PMID 24098781, 2013). "Increased vascular and coronary artery calcification has been linked to decreased MGP levels." (PMID 39246453, 2024). "This study was to investigate the role of serum Klotho, fetuin-A, and Matrix Gla Protein (MGP) in Coronary Artery Calcification (CAC) in patients with Maintenance Hemodialysis (MHD) and their predictive value for CAC." (PMID 39089098, 2024). "Vitamin K has been suggested to help avoid formation of coronary artery calcifications (CACs) due to the inhibitory effect of matrix Gla proteins (MGP-vitamin K2-dependent, Gla-containing MGPs) on mineral deposition in the arteries." (PMID 37513682, 2023). "Furthermore, the levels of both Fetuin-A and MGP in plasma exosomes were negatively while the levels of Annexin-A2 in plasma exosomes was positively correlated to coronary artery calcification scores (CACS)." (PMID 33585452, 2020). "Previous clinical studies have also shown that menaquinone supplementation was related to decreased coronary artery calcification (CAC) and decreased serum uncarboxylated MGP concentrations." (PMID 36632744, 2022).
coronary artery disease (10 papers, 2010 to 2025). "Background/Objectives: Vitamin K2 analogs are associated with decreased vascular calcification, which may provide protective benefits for individuals with coronary artery disease (CAD) by stimulating anti-calcific proteins like matrix Gla protein and adjusting innate immune responses." (PMID 39851476, 2025).
ovarian carcinoma (9 papers, 2018 to 2025). A malignant neoplasm originating from the surface ovarian epithelium. "For example, gene MGP, a member of the osteocalcin/matrix Gla protein family, has been reported to drive stemness and tumor initiation in ovarian cancer." (PMID 38168907, 2024). "To gain a better understanding of the role of MGP in drug resistance development, we used an ovarian cancer model, which is the most lethal gynecological malignancy." (PMID 30257426, 2018). "All ovarian cancer subtypes cells expressed MGP, with lower expression in serous and mucinous carcinoma (mild IRS score) when compared to endometrioid adenocarcinoma (moderate IRS score)." (PMID 30257426, 2018). "Immunofluorescence analysis confirmed elevated expression of MGP protein in investigated ovarian cancer cell lines, which indicates that MGP is equally expressed in all cells." (PMID 30257426, 2018). "In summary, to our knowledge, this is the first report about MGP expression in drug resistant cell lines and in ovarian cancer tissue at protein level." (PMID 30257426, 2018). "The results of our previous microarray tests indicated that MGP was overexpressed in five of eight drug-resistant ovarian cancer cell lines." (PMID 30257426, 2018). "In line with our findings concerning ovarian cancer, increased levels of MGP were found in glioblastomas, breast, cervical and skin cancer where positive correlation with tumor progression and survival was observed." (PMID 30257426, 2018). "Among them, we identified matrix Gla protein (MGP) with elevated expression levels in ovarian cancer cell lines resistant to PAC and TOP." (PMID 30257426, 2018). "The results of present research may improve our understanding of the role of MGP in ovarian cancer biology and help identify new therapeutic targets." (PMID 30257426, 2018). "Since we previously observed that COL3A1, LUM and MYOT (under review) are secreted to cell culture media in drug resistant ovarian cancer cell lines, we were interested whether MGP can also be present in the culture medium." (PMID 30257426, 2018). "Since MGP is expressed in two main transcript variants corresponding to two protein isoforms with molecular weight of 15.32 kDa (128 aa) (MGP-201) and 12.35 kDa (103 aa) (MGP-203), we compared the expression levels of both MGP transcripts in ovarian cancer drug sensitive and resistant cell lines." (PMID 30257426, 2018). "Finally, we detected expression of MGP protein in ovarian cancer lesions from different histological type of cancer." (PMID 30257426, 2018). "All of the ovarian cancer subtypes cells were positive for MGP." (PMID 30257426, 2018). "Immunohistochemical analysis of the MGP protein was performed in ovarian cancer patients." (PMID 30257426, 2018). "Because nothing is known about the mechanisms linking upregulation of MGP and resistance to chemotherapeutic drugs and, more generally, about the function of MGP in ovarian cancer, we hypothesized that MGP promotes ovarian cancer progression and resistance to chemotherapy." (PMID 30257426, 2018). "Additionally, analysis of paraffin sections confirmed the presence of MGP in ovarian cancer tissue." (PMID 30257426, 2018). "MGP is an important factor that might contribute to cancer resistance mechanism by augmenting the interaction of cells with ECM components leading to increased resistance of ovarian cancer cells to paclitaxel and topotecan." (PMID 30257426, 2018). "The research found elevated levels of MGP expression in PAC and TOP resistant ovarian cancer cell lines and corresponding media as well as in response to short time PAC and TOP treatment." (PMID 30257426, 2018). "Therefore, we have demonstrated that MGP is an important factor that might contribute to cancer resistance mechanism by augmenting the interaction of cells with ECM components leading to increased resistance of ovarian cancer cells to paclitaxel and topotecan." (PMID 30257426, 2018).
ovarian carcinoma (continued). "A detailed MGP expression analysis in sensitive (A2780) and resistant to paclitaxel (PAC) (A2780PR) and topotecan (TOP) (A2780TR) ovarian cancer cell lines and their corresponding media was performed." (PMID 30257426, 2018). "In this study, we performed detailed expression analysis of MGP at mRNA and protein levels in sensitive (A2780) and resistant to paclitaxel (A2780PR1) and topotecan (A2780TR1 and A2780TR2) ovarian cancer cell lines and their corresponding media." (PMID 30257426, 2018). "Notably, among the proteins unique to OCSCs, we identified Matrix Gla protein (MGP) that we recently reported as a driver of stemness and tumor initiation in ovarian cancer." (PMID 40204276, 2025). "Additionally, we explored the detailed distribution of MGP, COL8A2, and PAPPA in ovarian cancer using single-cell RNA transcriptome data (GSE147082) from the TISCH database." (PMID 37777759, 2023). "Therefore, we decided to investigate the expression profile of MGP in PAC- and TOP-resistant ovarian cancer cell lines in more detail." (PMID 30257426, 2018).
type 2 diabetes (9 papers, 2010 to 2025). "High plasma levels of dephosphorylated uncarboxylated MGP (dp-ucMGP) correlate with an increased cardiovascular risk in type 2 diabetes patients." (PMID 33808652, 2021). "The aim of this study was to evaluate factors associated with sensitive diabetic neuropathy in Type 2 Diabetes, and, in particular, dephospho-uncarboxylated MGP (dp-ucMGP), the inactive form of MGP." (PMID 32092076, 2020). "MGP undergoes γ-carboxylated at Glu residues under the influence of vitamin K and uncarboxylated forms of MGP in the circulation have been associated with arterial stiffness in adults, and with peripheral arterial calcification and incidence of cardiovascular events in patients with Type 2 diabetes." (PMID 29966260, 2018). "There are few data on (i) the levels of different MGP forms in a selected population with type 2 diabetes and (ii) the relationships between these various forms and peripheral artery calcification." (PMID 24762216, 2014).
colon carcinoma (8 papers, 2009 to 2023). "For example, the downregulation of MGP has been proposed as a hallmark of colon carcinoma, but other investigators reported that colon cancer progression and worse prognosis are rather associated with higher MGP expression." (PMID 36977707, 2023). "MGP was upregulated in different stages of colon cancer and associated with a worse prognosis." (PMID 35069573, 2021). "Zhang and colleagues showed that a high expression of matrix Gla protein (MGP) was correlated with colon cancer (CC) progression." (PMID 32405535, 2020). "However, the biological function of MGP inside cancer cells and its role in colon cancer (CC) remain largely unknown." (PMID 32405535, 2020). "There has been a positive correlation of MGP expression with tumor progression and poor prognosis in glioma, but a negative correlation of MGP expression with tumor progression and metastasis in renal and prostate carcinoma and decreased MGP has been found in colon carcinoma." (PMID 25210519, 2014). "We identified seven EMT-related genes (TPM1, LAMC1, POSTN, CCN1, MGP, PCOLCE2, and DPYSL3) with prognostic significance in patients with colon cancer from TCGA and GSE17536 cohorts." (PMID 34180352, 2021). "Four genes that are involved in calcium binding or signaling were co-regulated with TAZ-AXL-CTGF in the colon cancer specimens, including FBN1, CALD1, MGP and MYL9." (PMID 23372686, 2013). "Interestingly, multiple genes involved in calcium signaling (FBN1, CALD1, MGP and MYL9) were co-overexpressed with TAZ-AXL-CTGF in colon cancer." (PMID 23372686, 2013).
nephrolithiasis (8 papers, 2013 to 2022). The presence of a calculus in the pelvis of the kidney; this is most often composed of mineral salts and proteins. "Some macromolecules, such as osteopontin (OPN), matrix Gla protein (MGP), bikunin, and Tamm-Horsfall proteins, have been identified in both the urine and kidney stone matrix, and their gene variants have also been reported to affect the risk of kidney stone disease." (PMID 31772715, 2019). "For example, specific polymorphisms of the genes encoding vitamin D receptor (VDR), vascular endothelial growth factor (VEGF), androgen and estrogen receptors, calcium-sensing receptor (CASR), matrix Gla protein (MGP), and fibronectin (FN 1) were suggested to be a risk factor for nephrolithiasis." (PMID 24023817, 2013). "Fourth, decreased expression of calcification inhibitors, including OPN, MGP, and fetuin-A, has been observed in vascular calcification and nephrolithiasis." (PMID 33808324, 2021). "MGP, the most vigorous inhibitor of tissue calcification, participated in both vascular calcification and kidney stone formation, proven by numerous animal studies." (PMID 33808324, 2021). "g. fetuin-A, matrix Gla protein, etc.)may be the link between vascular calcification and nephrolithiasis." (PMID 36233750, 2022). "Compared to OPN and Fetuin-A, MGP might be the most important inhibitor of vascular calcification and nephrolithiasis." (PMID 33808324, 2021). "Moreover, in vivo, supplementation with vitamin K1 was found to inhibit the development and progression of nephrolithiasis through the upregulation of MGP in kidney tissues." (PMID 32839405, 2020). "MGP is also expressed in kidney and may inhibit the formation of kidney stones, which mainly consist of another crystalline phase, calcium oxalate monohydrate." (PMID 24265810, 2013).